NPW (neuropeptide W)
Description:
Plays a regulatory role in the organization of neuroendocrine signals accessing the anterior pituitary gland. Stimulates water drinking and food intake. May play a role in the hypothalamic response to stress (By similarity). NPW23 activates GPR7 and GPR8 more efficiently than NPW30.
Synonyms: PPL8; PPNPW; L8; L8C
Tractability: Antibody: UniProt places it where antibodies can reach, with high confidence; its Gene Ontology location is reachable by antibodies, with high confidence; UniProt predicts a signal peptide or a membrane-spanning region.
Gene: Protein-coding gene on chromosome 16 (2,009,926 to 2,020,755, forward strand). Ensembl gene ENSG00000183971.
Subcellular location: Secreted
Pathways (Reactome):
Signal Transduction: G alpha (i) signalling events; Peptide ligand-binding receptors
Gene Ontology:
Molecular function: protein binding; G protein-coupled receptor binding
Biological process: feeding behavior; G protein-coupled receptor signaling pathway
Cellular component: extracellular region
Genetic constraint (gnomAD): Loss-of-function variants: 6 observed, 4.21 expected, observed/expected ratio (o/e) 1.43, 90% interval 0.73 to 1.92. That is too few expected variants to judge how well the gene tolerates losing a copy. Missense variants: 274 observed, 162.23 expected, observed/expected ratio (o/e) 1.69, 90% interval 1.53 to 1.86. Synonymous variants: 132 observed, 79.74 expected, observed/expected ratio (o/e) 1.66, 90% interval 1.44 to 1.89.
Homologues: Orthologues: chimpanzee NPW (98% identical), macaque NPW (73% identical), mouse Npw (58% identical), rat Npw (56% identical), pig NPW (55% identical), zebrafish npb (18% identical), tropical clawed frog npb (18% identical). Paralogues in human: NPB (25% identical).
Diseases named in the same sentence as NPW in open-access papers:
NPW is named in the same sentence as 8 diseases in open-access papers, as found by Europe PMC text mining. Sharing a sentence is not in itself a finding about the gene and the disease. The quoted sentences say what the papers report.
anorexia nervosa (1 paper, 2018). A disorder most often seen in adolescent females characterized by a refusal to maintain a minimally normal body weight, an intense fear of gaining weight, a disturbance in body image, and, in postmenarcheal females, the development of amenorrhea. "The aim of the study was to assess the correlation between the levels of neuropeptide B, neuropeptide W, vaspin, and the total antioxidant status in the blood, as well as nutritional status of patients with anorexia nervosa." (PMID 29984256, 2018). "The aim of the study was to assess the correlation between the levels of neuropeptide B (NPB), neuropeptide W (NPW), vaspin (VAS), and the total antioxidant status (TAS) in the blood, as well as nutritional status of patients with anorexia nervosa (AN)." (PMID 29984256, 2018).
Anxiety (1 paper, 2020). Intense feelings of nervousness, tension, or panic often arise in response to interpersonal stresses. "Neuropeptide W (NPW) is a peptide hormone, originally isolated from porcine hypothalamus, that plays an important role in the regulation of feeding and drinking behavior, stress responses, emotion, anxiety and fear 4-6." (PMID 33061795, 2020).
carcinoids (1 paper, 2022). "Interestingly, some of the peptidergic genes expressed in only minor subpopulations of normal PNECs (e.g. NPW, NPPA, SST, CARTPT) were detected in many carcinoids, whereas the nearly ubiquitous PNEC peptidergic gene CALCA was absent from most carcinoids." (PMID 36469459, 2022).
migraine (1 paper, 2022). "Neuropeptides directly associated with pain or migraine from significantly differentially expressed neuropeptide prohormone genes include apelin (APLN), cortistatin (CORT), IGF2, neuromedin B (NMB), neuropeptide W (NPW), PDGFA and platelet-derived growth factor, D polypeptide (PDGFD), TAC4, and VIP." (PMID 35453627, 2022).
neuroblastoma (1 paper, 2010). Neuroblastoma (NB) is the most common solid, extracranial childhood tumor. "The five genes identified as candidate genes involved in neuroblastoma progression were: MYCN (neuroblastoma derived), NPW (neuropeptide W), SLC30A3 (solute carrier family 30, member 3), MYCNOS (neuroblastome derived opposite strand), and MYCN* (v-myc myelocytomatosis viral related oncogene)." (PMID 20380745, 2010).
Obesity (1 paper, 2021). Accumulation of substantial excess body fat. "NPBWR is a receptor for the neuropeptide W and neuropeptide B. Ablation of this receptor in mice leads to obesity, and NPBWR signaling has a role in the central regulation of energy balance." (PMID 34572017, 2021).
NPW also shares sentences with these, for which no sentence is quoted: cancer (1 paper); tumor (1).